RNU6-114P (RNA, U6 small nuclear 114, pseudogene)
Gene: Small nuclear RNA gene on chromosome X (3,572,857 to 3,572,961, forward strand). Ensembl gene ENSG00000207435.
Homologues: Orthologues: chimpanzee U6 (100% identical), dog U6 (79% identical), pig U6 (77% identical). Paralogues in human: RNU6-521P (89% identical), RNU6-59P (87% identical), RNU6-1145P (86% identical), RNU6-274P (86% identical), RNU6-310P (86% identical), RNU6-393P (86% identical), RNU6-41P (86% identical), RNU6-434P (86% identical), RNU6-797P (86% identical), RNU6-1031P (85% identical), RNU6-1047P (85% identical), RNU6-1181P (85% identical), and 1285 more.